IMPDH1P10 (inosine monophosphate dehydrogenase 1 pseudogene 10)
Gene: Processed pseudogene on chromosome 2 (201,137,516 to 201,140,027, reverse strand). Ensembl gene ENSG00000232133.
Diseases named in the same sentence as IMPDH1P10 in open-access papers:
IMPDH1P10 is named in the same sentence as 1 disease in open-access papers, as found by Europe PMC text mining. Sharing a sentence is not in itself a finding about the gene and the disease.
IMPDH1P10 shares sentences with these, for which no sentence is quoted: infection (1 paper).